ENSG00000289092 (novel transcript, antisense to NCOA4)
Gene: Long non-coding RNA gene on chromosome 10 (46,007,581 to 46,008,969, forward strand). Ensembl gene ENSG00000289092.
Gene Ontology:
Biological process: miRNA-mediated post-transcriptional gene silencing